PTX3 (pentraxin 3)
Diseases named in the same sentence as PTX3 in open-access papers (continued):
Sharing a sentence is not in itself a finding about the gene and the disease.
osteoarthritis (7 papers, 2020 to 2023). A noninflammatory degenerative joint disease occurring chiefly in older persons, characterized by degeneration of the articular cartilage, hypertrophy of bone at the margins and changes in the synovial membrane. "For example, in a mouse model of osteoarthritis, PTX3 deficiency significantly reduced the severity of the disease by alleviating cartilage degeneration and systemic inflammation." (PMID 38068970, 2023). "In fact, these authors documented a reduced expression of PTX3 (in terms of the PTX3+ area in immunohistochemical images of femoral head biopsies) in osteoporotic individuals compared to patients affected by osteoarthritis and healthy young subjects." (PMID 38068970, 2023). "The result obtained demonstrated the involvement of PTX3 in the inflammation cascade related to osteoarthritis, suggesting its potential function as a biomarker of disease activity in OA affected patients." (PMID 34067775, 2021). "Several groups found that PTX3 is upregulated in the serum of RA patients compared to healthy donors or patients with osteoarthritis." (PMID 34248970, 2021). "We have previously demonstrated that AFSC-extracellular vesicles contain anti-inflammatory molecules, namely, HFG, TGFβ, and pentraxin 3 that showed a therapeutic effect on osteoarthritis." (PMID 33193997, 2020).
polycystic ovary syndrome (7 papers, 2015 to 2025). A disorder that manifests as multiple cysts on the ovaries. "PTX3 also influences female infertility conditions, such as polycystic ovary syndrome (PCOS), a chronic inflammatory disorder characterized by hyperandrogenism, persistent anovulation, and polycystic ovarian changes." (PMID 41479916, 2025). "The ovarian PTX3 level in polycystic ovary syndrome (PCOS) remains uncertain." (PMID 33594624, 2021).
renal fibrosis (7 papers, 2017 to 2025). A final common manifestation of a wide variety of chronic kidney diseases characterized by glomerulosclerosis and tubulointerstitial fibrosis. "The PTX3 gene has been implicated in fibrotic diseases, such as pulmonary and renal fibrosis, and its inhibition reduced fibrosis in a mouse model." (PMID 38111581, 2023). "A recent study showed that long-term low-grade inflammation, with sustained increased PTX3 levels, may underlie renal fibrosis in ESRD due to a MMP-9/TIMP-1 imbalance." (PMID 31316299, 2019). "PTX3 induces mitochondrial dysfunction and renal tubular cell senescence via β-linker activation, leading to renal fibrosis." (PMID 40995516, 2025). "Another study reported that the JNK pathway plays an essential role in the PTX3-mediated promotion of renal fibrosis." (PMID 39451219, 2024). "In HK-2 cells and a rat unilateral ureteral obstruction model of renal fibrosis, pentraxin 3 upregulated EMT by activating JNK signaling." (PMID 36142408, 2022). "PTX3 deposition and renal fibrosis were also significantly lower in anti-PTX3 Ab-positive patients than negative patients." (PMID 33664737, 2020). "This study is aimed at evaluating the potential of PTX3 as a biomarker for multiple risk factors associated with ESRD, particularly inflammation, malnutrition, CVD, and renal fibrosis." (PMID 31316299, 2019). "Furthermore, PTX3 was the main inflammatory determinant of both cardiac and renal fibrosis markers (higher standardized beta value; lower p value) in these patients." (PMID 31316299, 2019). "Moreover, in vitro studies showed that PTX3 appears to contribute to renal fibrosis by promoting differentiation of monocytes into fibrocytes and upregulating epithelial-to-mesenchymal transition." (PMID 31316299, 2019). "Data support the clinical applicability of PTX3 as a broader inflammatory biomarker than the classical ones, presenting a close association with inflammation, malnutrition, CVD, and renal fibrosis and a great potential to predict all-cause mortality in dialysis patients." (PMID 31316299, 2019). "Nevertheless, the strong correlation found between the PTX3 levels and circulating TIMP-1 in our cohort of dialysis patients, as well as the regression data from the predictive analysis, supports a possible association between this modulator and renal fibrosis in ESRD patients." (PMID 31316299, 2019). "Levels of the cardiac and renal fibrosis markers and of the oxidized LDL/LDL-C ratio were found to be independent determinants of PTX3 concentration." (PMID 31316299, 2019). "Circulating levels of PTX3 and classical inflammatory mediators, including the clinical prototypical C-reactive protein (CRP), were assessed in 246 ESRD patients on dialysis and analysed in relation to the lipid profile, adipokine levels, and nutritional, cardiac, and renal fibrosis markers." (PMID 31316299, 2019).
steatosis (7 papers, 2008 to 2025). Increased lipid within the cytoplasm of cells. "Elevated PTX3 levels in NAFLD are associated with steatosis severity and hepatic enzyme abnormalities." (PMID 40951433, 2025). "In a separate study, PTX3 levels were found to be significantly higher in patients with non-alcoholic steatohepatitis (NASH) compared to those with simple steatosis." (PMID 41462970, 2025). "Using 1.61 ng/mL as a cutoff value, PTX3 had a fair performance in differentiating NASH from simple steatosis (AUROC 0.755, sensitivity 66.7%, specificity 78.6%)." (PMID 24252302, 2013). "Furthermore, plasma PTX-3 levels correlated with the NFSs and histologically verified fibrosis stage and steatosis grade." (PMID 40066165, 2025). "In adults, plasma PTX3 levels correlate significantly with NAFLD activity score, fibrosis stage, and steatosis grade (r = 0.659, P < 0.001; r = 0.354, P < 0.01; r = 0.455, P < 0.001)." (PMID 40951433, 2025). "Analysis of the plasma PTX3 levels in relation to the histological grade of steatosis or grade of necroinflammation showed no relation between the plasma PTX3 levels and either of the two other parameters (p = 0.1554, p = 0.1745, respectively by Kruskal-Wallis test)." (PMID 19014569, 2008).
tuberculosis (7 papers, 2012 to 2025). A chronic, recurrent infection caused by the bacterium Mycobacterium tuberculosis. "A study investigating 70 biomarkers associated with infection and inflammation in tuberculosis patients identified PTX3 as one of seven elevated proteins linked to disease severity, smear grading, and extensive imaging lesions." (PMID 40313930, 2025). "It would also be worthwhile to determine any additional role for PTX3 plays additional roles in context with tuberculosis and its associated outcomes in the lungs." (PMID 23755050, 2013). "Plasma level of PTX3 is found to be correlated with the clinical severity of tuberculosis and therefore is seen as an appropriate indicator of the disease stage." (PMID 23755050, 2013). "PTX3 level declines with the success of therapeutic treatment against tuberculosis but increases again when treatment fails." (PMID 23755050, 2013). "Similarly, a separate study involving 220 tuberculosis patients demonstrated significantly higher plasma PTX3 levels in tuberculosis patients compared to healthy controls." (PMID 40313930, 2025). "In a study of 213 tuberculosis patients in West Africa, two SNPs—rs1840680 and rs2305619 —in the PTX3 gene were found to be less frequent in the TB group compared to healthy controls, indicating that these genotypes may confer protection against tuberculosis infection." (PMID 40313930, 2025). "Although PTX3 is not specific for diagnosing tuberculosis, its detection can help monitor disease activity and treatment efficacy." (PMID 40313930, 2025).
acute appendicitis (6 papers, 2020 to 2024). "In addition to standard biomarkers, several new biomarkers for acute appendicitis, such as hyponatremia, hyperfibrinogenemia, hyperbilirubinemia, pentraxin-3 (PTX-3), neutrophil gelatinase-associated lipocalin (NGAL), or interleukin-6 (IL-6), have recently been investigated." (PMID 37189999, 2023). "Also, only two of them assessed the association of IL-6 and PTX3 with appendicitis." (PMID 32983691, 2020). "There are, however, multiple papers on the role of PTX-3, IL-6, D-dimer, and CRP in other settings of urgent acute abdomen, such as acute appendicitis, one of the main diagnostic entities to consider in the differential diagnosis of ovarian torsion." (PMID 39519217, 2024). "This article breaks down the previous research on pentraxin-3 and interleukin-6 biomarkers in relation to appendicitis and proposes a new hypothetical way of confirming the diagnosis." (PMID 32983691, 2020). "The next study testing the PTX3 role in appendicitis was conducted in 2019 on 172 adult patients divided into three groups." (PMID 32983691, 2020). "However, biomarkers such as pentraxin-3 and interleukin-6 have been recently researched to assess the possibility of confirming the diagnosis of acute appendicitis in both adults and the pediatric age group." (PMID 32983691, 2020). "Therefore, further studies on a multicenter level are needed to explore the role of PTX3 and IL-6 in acute appendicitis alongside the Alvarado Score." (PMID 32983691, 2020). "However, the previous studies show how PTX3 with the aid of IL-6 might change that in the near future by not only diagnosing acute appendicitis but also predicting the likelihood of perforation in those individuals." (PMID 32983691, 2020). "PTX3-levels are elevated in AA, but differentiation between perforated and non-perforated appendicitis demands other methods." (PMID 35704081, 2022). "Nevertheless, PTX3 does not seem to distinguish between perforated and non-perforated AA, as the analysis of the pooled data did not yield a statistically significant rise in PTX3 levels among patients with perforated appendicitis." (PMID 35704081, 2022). "Group 1 in our study served to delimit the baseline values of the molecule in a healthy population, but we do not believe it should be included the analysis, because it is not representative of the patients in whom PTX3 will be used to diagnose acute appendicitis in the clinical setting." (PMID 36454367, 2022).
age-related macular degeneration (6 papers, 2016 to 2021). Age-related loss of vision in the central portion of the retina (macula), secondary to retinal degeneration. "Finally, a protective role for PTX3 in response to complement dysregulation was also demonstrated in age-related macular degeneration (AMD), the leading cause of blindness worldwide." (PMID 34572075, 2021). "Taken together, these results provide critical insights into the pathologic effects of PTX3 during oxidative stress in the early development of age-related macular degeneration." (PMID 31795454, 2019). "Both CRP and PTX3 are expressed and upregulated under inflammatory conditions and may deposit locally at the site of tissue damage, also in complement-related diseases such as age-related macular degeneration and atypical hemolytic uremic syndrome." (PMID 32765490, 2020).
cerebrovascular diseases (6 papers, 2015 to 2022). "Prior literature regarding the association of PTX3 in cerebrovascular disease has incompletely established the relationship of PTX3 and CAS complexity and severity." (PMID 31998222, 2019). "The acute phase protein long pentraxin-3 (PTX3) is an important regulator of peripheral innate immunity and a key mediator of inflammation during cardiovascular and cerebrovascular diseases." (PMID 36012705, 2022). "This study aims to more thoroughly evaluate the association of plasma PTX3 levels and the prevalence and severity of CAS in patients with cerebrovascular disease." (PMID 31998222, 2019). "The acute phase protein pentraxin-3 (PTX3) is an important regulator of peripheral innate immunity and is now recognised as key mediator of inflammation during cardiovascular and cerebrovascular diseases." (PMID 25616391, 2015). "PTX3 is initially considered as a marker of inflammatory response, and it is involved in the occurrence and development of a variety of inflammatory diseases, including inflammatory related tumors, cardiovascular and cerebrovascular diseases, and neuroinflammation." (PMID 31957804, 2020). "A new regulator of angiogenesis is the acute phase protein pentraxin 3 (PTX3), the function of which in cardiovascular and cerebrovascular disease is emerging." (PMID 30315331, 2018). "Pentraxin 3 (PTX3), an acute-phase inflammation protein produced by several cell types, has long been described as a possible biomarker for age-related cardiovascular and cerebrovascular diseases." (PMID 30733816, 2019). "Plasma levels of LDL-C, TNF-α, and PTX3 were increased significantly in the CAS group patients vs. the CAS-free group (p = 0.002, 0.002, 0.000, respectively), and family history of cerebrovascular disease was significantly more common in the CAS group (p = 0.005)." (PMID 31998222, 2019). "Within the CAS group, LDL-C, TNF-α, and PTX3 were significantly elevated in the SS group (p = 0.049, 0.002, 0.001, respectively) compared to the MS group, however no statistical difference infamily history of cerebrovascular disease was noted between these two groups (p = 1.000)." (PMID 31998222, 2019).
endometriosis (6 papers, 2020 to 2024). The growth of functional endometrial tissue in anatomic sites outside the uterine body. "Silencing LOX and PTX3 expression using small molecules is a potential treatment strategy for reducing cell migration, invasion, and proliferation, especially in deep infiltrating endometriosis with KRAS and PIK3CA mutations." (PMID 34202354, 2021). "In our preliminary analysis, PTX3 appears to be a potential candidate crucial for the inhibition of endometriosis by ADSC-CM." (PMID 37293500, 2023). "IPA demonstrated that PTX3 was potentially critical for the inhibition of endometriosis by ADSC-CM due to its anti-inflammatory and antiangiogenic properties as well as its importance in implantation." (PMID 37293500, 2023). "Our findings suggest that inhibition of LOX and PTX3 may be an alternative therapeutic strategy to reduce the incidence of endometriosis." (PMID 34202354, 2021). "Thus, inhibition of KRAS/PIK3CA, or their downstream targets such as LOX or PTX3 inhibitors, might be clinically effective in progestin-resistant endometriosis-related pain." (PMID 38666954, 2024). "In an endometriosis rat model, the angiotensin II receptor blocker losartan reduced TGF-β, and the surface area of endometriosis lesions was decreased as were the plasma levels of the angiogenic factors and inflammatory markers VEGF, TNF-α, PTX-3, and CRP." (PMID 35628346, 2022). "Therefore, LOX and PTX3 may be potential therapeutic targets for aggressive endometriosis." (PMID 34202354, 2021).
fibrosarcoma (6 papers, 2018 to 2024). A malignant mesenchymal fibroblastic neoplasm affecting the soft tissue and bone. "The pattern recognition receptor PTX3 has been proposed as an extrinsic oncosuppressor, genetic loss of PTX3 in Ptx3−/− mice increasing tumor growth in carcinogen-induced models of fibrosarcoma and skin cancer." (PMID 30443492, 2018). "Indeed, genetic loss of PTX3 in PTX3−/− mice increases the incidence of cancer development and growth in carcinogen-induced models of fibrosarcoma and skin cancer." (PMID 30443492, 2018). "In fibrosarcoma, tumor-infiltrating lymphocytes also appear to be influenced by PTX3 gene expression, suggesting its broader impact on immune cells within the tumor microenvironment." (PMID 39594709, 2024). "Together, these data show that PTX3 overexpression exerts a relevant anti-tumorigenic activity in fibrosarcoma accompanied by a significant conditioning of tumor microenvironment in terms of angiogenesis and inflammatory infiltrate." (PMID 31533326, 2019). "PTX3 overexpression resulted in a significant reduction in the levels of C3 immunoreactivity in fibrosarcoma grafts." (PMID 31533326, 2019). "Overall, these data strongly correlate the tumor-impairing activity of PTX3 expressed by tumor cells or by tumor stroma with a reduced neovascular response and a significant decrease of inflammatory infiltrate in these fibrosarcoma models." (PMID 31533326, 2019). "Our study shows for the first time that PTX3 overexpression hampers the tumorigenic potential of fibrosarcoma cells and that stromal PTX3 accumulation in transgenic TgN(Tie2-hPTX3) mice significantly inhibits the growth of syngeneic fibrosarcoma tumor grafts." (PMID 30443492, 2018). "Here, we demonstrate that PTX3 overexpression significantly reduced the proliferative and tumorigenic potential of fibrosarcoma cells in vitro and in vivo." (PMID 30443492, 2018). "Here, PTX3 overexpression significantly reduced the proliferative and tumorigenic potential of fibrosarcoma cells in vitro and in vivo." (PMID 30443492, 2018). "PTX3 overexpression significantly reduced the proliferation rate of both murine and human fibrosarcoma transfectants when compared to controls, with a significant decrease of their clonogenic capacity." (PMID 30443492, 2018). "The inflammation-associated long pentraxin 3 (PTX3) was found to reduce FGF-2-mediated angiogenesis, but its role on fibrosarcoma immune inflammatory infiltrate is still unknown." (PMID 31533326, 2019). "Notably, the impact of PTX3 on fibrosarcoma microenvironment results in a decrease of immune/inflammatory components regardless from its cellular source (i.e., grafted tumor cells or endothelium of the host)." (PMID 31533326, 2019). "Indeed, we show that PTX3 reduces the level of complement 3 (C3) deposition reducing fibrosarcoma progression." (PMID 31533326, 2019). "In this study, we have evaluated the effect of PTX3 on tumor vascular density and mast cell, macrophage and T-lymphocyte infiltrates in a murine fibrosarcoma model in which PTX3 was overexpressed by grafted fibrosarcoma cells or by the endothelium of the host animals." (PMID 31533326, 2019). "Interestingly, PTX3 expression has been described as epigenetically downregulated in various types of tumors, including fibrosarcoma, and its overexpression has been proven to be sufficient to reduce tumor burden." (PMID 31533326, 2019). "In addition, systemic delivery of human PTX3 driven by the Tie2 promoter inhibited the growth of fibrosarcoma grafts in transgenic mice." (PMID 30443492, 2018). "In addition, PTX3 overexpression driven by the Tie2 promoter inhibits the growth of syngeneic fibrosarcoma tumor grafts in transgenic mice." (PMID 30443492, 2018). "In a fibrosarcoma model, PTX3 overexpression or treatment with the small molecule pan-FGF trap NSC12 significantly reduced the proliferative and tumorigenic potential of fibrosarcoma cells in vitro and in vivo." (PMID 34204560, 2021).
fibrosarcoma (continued). "In this study, we have evaluated the PTX3 activity on immune infiltrating mast cells, macrophages and T-lymphocytes by immunohistochemistry on murine MC-TGS17-51 fibrosarcoma cells and on transgenic TgN(Tie2-hPTX3) mouse." (PMID 31533326, 2019). "PTX3, on the other hand, has demonstrated its capacity toinhibitfibroblast growth factors (FGF)-mediated angiogenesis and impede thegrowth and vascularization of FGF-dependent tumors, as observed incases of fibrosarcoma." (PMID 38809962, 2024). "On this basis, to assess the effect of the local/systemic delivery of PTX3 protein on fibrosarcoma growth, wild type MC17-51 cells were injected in syngeneic wild type (C57BL/6) and transgenic TgN(Tie2-hPTX3) mice that overexpress human PTX3 under the endothelial specific Tie2 promoter." (PMID 30443492, 2018). "In this frame, the PTX3-derived small molecule FGF-trap NSC12 may pave the way to the discovery of novel drug candidates for those subsets of soft tissue sarcomas, including fibrosarcomas, in which FGFR ligands play an onco-driving role." (PMID 30443492, 2018). "Finally, notwithstanding the complexity of the mechanism of action of PTX3 on different molecular and cellular components of the tumor and host, our results support the hypothesis that anti-FGF/FGFR strategies may exert a therapeutic effect in fibrosarcoma." (PMID 31533326, 2019).